RBM47 (RNA binding motif protein 47)
Diseases named in the same sentence as RBM47 in open-access papers (continued):
Sharing a sentence is not in itself a finding about the gene and the disease.
tumor (continued). "Consistent with these investigations, the present study showed that RBM47 suppressed EOC cell proliferation, and thus we concluded that IDH1-AS1 inhibited EOC cell proliferation and tumor growth by upregulating RBM47 mediated by miR-518c-5p." (PMID 37981573, 2023). "In our study, we also identified the performance of RBM47 as a tumor suppressor in HCC, including inhibiting tumor growth and metastasis." (PMID 35831298, 2022). "Taking into consideration of the enrichment of GO and KEGG, the Upframeshift 1 (UPF1), which is a tumor suppressor in HCC, was predicted to be a direct target of RBM47." (PMID 35831298, 2022). "RBM47 suppresses Nrf2 activity by upregulating KEAP1 and CUL3, and suppressing some Nrf2 activators, leading to the inhibition of tumor growth in vivo." (PMID 34804951, 2021). "NOL12, PABPC1L, RNASE2, RPL22L1, OASL, and YBX3 expression were significantly positively correlated with tumor grade and AJCC stage, while RBM47 expression was negatively correlated with tumor grade and AJCC stage." (PMID 33229623, 2020). "Likewise, RBM47 was later found to bind to the 3′UTR of AXIN1 mRNA and stabilize it, leading to the disruption of Wnt/β-catenin signaling and tumor progression in NSCLC." (PMID 41516083, 2025). "Then, immunohistochemistry was performed to detect RBM47 and Ki67 protein expression in tumor tissues, identifying that RBM47 protein was highly expressed, while Ki67 protein was lowly expressed in IDH1-AS1-overexpressing tumor tissues." (PMID 37981573, 2023). "However, there is evidence that UPF1 acts as a tumor suppressor in HCC, and RBM47 reveals clinical value in some other cancers." (PMID 35831298, 2022). "Although these prognostic DE RBPs were documented to be involved in tumor development, the functions and mechanisms of the remaining DE RBPs other than RBM47 have not been fully elucidated." (PMID 33224957, 2020). "Therefore, RBM47 is also repressed by EMT-TFs, which are up-regulated in cancer cells during tumor progression and mediate EMT, thereby promoting invasion and presumably metastasis." (PMID 28680090, 2017). "Interestingly, comparison of the CRC cell line pair SW480/SW620, which both originate from the same patient – SW480 from the primary tumor and SW620 from a lymph node metastasis – showed an elevated expression of RBM47 in the SW620 cells." (PMID 28680090, 2017). "Consequently, the repression of RBM47 may result from a combination of a decrease of FOXA1 expression and the activation of the RBM47-repressing factors, such as STAT3, during tumor progression." (PMID 41335176, 2025). "The results showed that the size, volume, and weight of xenograft tumors in the Lv-RBM47 group were remarkably lower than those in the NC group, whereas sh-SNHG5 co-transfection could rescue the inhibitory effect of RBM47 overexpression on tumor growth." (PMID 35338124, 2022). "Several outlier genes whose knockdown confers striking vulnerability are tumor suppressors including APC, PHLPP1 and SPEN, while a number of other candidates have been reported to harbor anti-oncogenic activities such as the pro-apoptotic gene MTCH2 and the anti-metastatic RNA chaperone RBM47." (PMID 27296290, 2016). "Interestingly, the RBM47 promoter methylation was similar in normal tissue and stage I tumors, but increased in higher stage tumors, suggesting the RBM47 promoter hypermethylation does not occur during tumor initiation, but during tumor progression." (PMID 41335176, 2025). "Interestingly, the DEGs of RBM47-OE are enriched in these related pathways, which implies RBM47 may regulate CRC cell proliferation by itself ISGylation, stabilizing mRNA, and alternative splicing of downstream immune response and tumor suppression-related genes." (PMID 40695891, 2025). "This suggested that RBM47 may not necessarily have a direct tumor suppressive signaling function." (PMID 24898756, 2014).
tumor (continued). "Real-time quantitative PCR results disclosed that MPC1, ZG16, RBM47, CPM and DNASE1L3 were expressed at higher levels in adjacent normal tissues than in tumor tissues, and SMOX expression was higher in tumor tissues than in non-tumor tissues." (PMID 38914961, 2024).
cancer (25 papers, 2014 to 2026). A tumor composed of atypical neoplastic, often pleomorphic cells that invade other tissues. "The down-regulation of RBM47 has been consistently associated with aggressive cancer phenotypes, making it a promising biomarker for CRC progression." (PMID 41335176, 2025). "Decreased expression of RBM47 has been implicated in promoting proliferation and metastasis across various cancers, including breast cancer, lung adenocarcinoma, and CRC." (PMID 39350250, 2024). "Subsequently, increased RBM47 levels in cancer tissue samples were strongly linked to the clinicopathological characteristics of CC and served as independent predictors of extended OS and DFS." (PMID 38914961, 2024). "This study not only elucidates the mechanism underlying RBM47 inactivation but also underscores a promising therapeutic target for cancer treatment." (PMID 39350250, 2024). "While we did not observe any mutations at the K329 locus, we identified several RBM47 mutations located adjacent to K329 in cancer patients, including S309L, S325P, Y327S, and A330V mutations." (PMID 38036512, 2023). "Our findings discovered that RBM47 mutations in close proximity to K329, including S309L, S325P, Y327S, and A330V, observed in human cancers according to the COSMIC database, impair RBM47-ISGylation." (PMID 38036512, 2023). "Furthermore, Rbm47-IKO mice were protected against colitis-associated cancer." (PMID 37014710, 2023). "One recent study has summarized the functions of RBM47 in vertebrate development and cancers by post-transcriptional regulation." (PMID 40695891, 2025). "Our results extend the understanding of RBM47 function in cancer cells, and the identified molecular targets can be served as potential therapeutic targets for CRC in future." (PMID 40695891, 2025). "RBM47 is highly expressed in epithelial-like cancer cells, whereas decreased RBM47 expression was found in mesenchymal-like cancer cells, which are generally more invasive and metastatic than epithelial-like CRC lines." (PMID 41335176, 2025). "Various cancer types can be affected by the aberrant expression of RBM47, which can affect transcriptional and post-transcriptional regulation." (PMID 38914961, 2024). "Nevertheless, it is unclear exactly how RBM47 contributes to cancer cell immunity and CC development." (PMID 38914961, 2024). "Prior studies have demonstrated the significance of RBM47 in the post-transcriptional regulation of IL-10, thereby enhancing the regulatory capabilities of B cells and implicating RBM47 in cancer immunity modulation." (PMID 38914961, 2024). "Bioinformatics analysis and research results prompted that RBM47 was reduced in ccRCC cancer tissues in TCGA-KRIC, ICGC, GEO, CPTAC, and clinical samples, its low expression indicated poor prognosis in ccRCC." (PMID 37962768, 2023). "We investigated RBM47 expression across various cell lines, including the human cancer cell line A549." (PMID 38036512, 2023). "RBM47 can induce targeted RNA partners’ inactivation and inhibit cancer progression through downstream signaling in breast cancer." (PMID 37962768, 2023). "We next explored the role of RBM47 expression and function in deidentified human patients with CRC and found that RBM47 mRNA was significantly downregulated in cancer tissue compared with paired uninvolved tissue." (PMID 37014710, 2023). "We have recently learned that the dysregulation of the RBMP RNA-binding motif protein 47 (RBM47), which contributes to various mRNA-related pathways, is related to cancer." (PMID 35831298, 2022). "For example, apical localization of wg RNA is essential for signal activation in epithelial cells, whilst the RNA binding protein RBM47 regulates Wnt signaling in zebrafish head development as well as in cancer." (PMID 27536874, 2016). "As expected, the RBM47I281fs-expressing tumors contained only weakly staining cancer cells intermingled with small cells with strong RBM47 expression, similar to those seen in normal lung parenchyma." (PMID 24898756, 2014).
cancer (continued). "In summary, these results demonstrate the important roles of RBM47 in inhibiting cancer progression, while the underlying mechanism are not well investigated." (PMID 40695891, 2025). "These previous studies provide an important hint that whether RBM47 exerts cancer-promoting or cancer-suppressing effects depends on the type of cancer." (PMID 39741300, 2024). "Several studies have reported the different role of RBM47 in cancer progression." (PMID 39741300, 2024). "Our results also propose that reinstating RBM47 could serve as a promising strategy for anti-cancer treatment." (PMID 38914961, 2024). "The results showed that the expression profile of RBM47 varied in different types of cancers." (PMID 39741300, 2024). "RBM47 is dysregulated in various cancers and is involved in cancer progression." (PMID 37660095, 2023). "A large proportion (47 RBPs) are commonly regulated in both RSCC and LSCC with several enriched for binding among DEGs (adj p < 0.05), including RBPs previously discussed in the context of CRC such MSI2, MEX3A, IGF2BP1/3, ELVAL4, and cancers in general, such as RBM47, DKC1, CELF4, ELAVL3." (PMID 32293332, 2020). "This revealed that some cancer clones were able to form robust lung metastasis even in the presence of RBM47, but that many of the metastases formed after the inoculation of wild type RBM47-expressing cells had avoided or suppressed the expression of RBM47." (PMID 24898756, 2014). "The effects of reduced RBM47 activity on cancer cell fitness, determined by the sum phenotypic output of all regulated target transcripts, may therefore vary depending on the context." (PMID 24898756, 2014). "Further work is needed to test if increasing RBM47 activity could be used as a new treatment for some types of cancer." (PMID 24898756, 2014). "However, the mechanisms underlying RBM47 repression during cancer progression are not well understood." (PMID 41335176, 2025). "However, few studies have demonstrated that RBM47 could interact with lncRNA to regulate cancer progression." (PMID 37660095, 2023). "Therefore, our results suggest that RBM47, as a new molecular biomarker, may play a key role in the cancer development of ccRCC." (PMID 37962768, 2023). "Interestingly, RBM47 has opposing roles in different cancers, although it mainly functions as an RBP and may even exert regulatory effects on DNA." (PMID 35831298, 2022). "At transcriptional regulation, RBM47 may reveal an ambiguous role in cancer." (PMID 35831298, 2022). "Scatter plots of UCS cancer tissues confirmed positive correlations between PSI values of KRAS E4 and mRNA expression levels of RBM47 and PTBP1." (PMID 41368203, 2026). "To validate the RNA-seq analysis, we selected seven representative genes on the basis of their relevance for HGSOC (PAX8, EGFR) and other cancers (GATA6, RBM47, KHDRBS3), or for their involvement in the DDR pathway (ATRIP, POLH)." (PMID 37202753, 2023). "RBM47 acts as a multifunctional RBP modulating alternative splicing and the abundance of several mRNAs, which can lead to inhibition of cancer progression." (PMID 24898756, 2014). "Thus far, these results demonstrate that RBM47 is a direct target gene of LINC00862 and its expression levels modulate LINC00862-mediated anti-cancer effects." (PMID 41487470, 2026). "Based on these profiles, we hypothesized that RBM47 and PTBP1 regulate the alternative splicing of KRAS E4, consistent with the positive correlations observed in TCGA cancer tissues." (PMID 41368203, 2026). "Overall, our findings indicate that RBM47 and PTBP1 regulate the alternative splicing of KRAS E4 in human cancers, and that the resulting KRAS4A splicing isoforms may promote cancer cell proliferation and metastasis." (PMID 41368203, 2026). "Additionally, we identified that the mRNA expression of splicing factors RBM47 and PTBP1 positively correlates with KRAS E4 inclusion rates in cancer tissues and confirmed their roles in enhancing E4 inclusion in KRAS mRNA." (PMID 41368203, 2026).
cancer (continued). "In summary, our study highlights the anti-cancer function of RBM47 in HCT116 cells, as well as the potential molecular targets, especially for the alternative splicing events and genes, regulated by RBM47." (PMID 40695891, 2025). "RBM47 modulates the splicing of CD44, which is a marker of cancer stem cells." (PMID 40695891, 2025). "In view of the important role of cell metabolism in cancer progression, we performed the non-target metabolomics analysis to figure out metabolic changes in response to RBM47 knockdown." (PMID 39741300, 2024). "This may be explained by direct repression of RBM47 via the EMT-inducers STAT3 and SNAIL, which are generally activated in mesenchymal-like, invasive cancer cells." (PMID 28680090, 2017). "The catalogue of somatic mutations in cancer (COSMIC) database reported 9 non-synonymous mutations in RBM47, three of which were frameshift mutations truncating one or more of the RRM domains." (PMID 24898756, 2014). "Finally, we identified RBM47 and PTBP1 as regulators of KRAS E4 alternative splicing in cancer." (PMID 41368203, 2026). "RBM47 is repressed by several EMT-related transcription factors, such as snail family transcriptional repressor 1 (SNAIL), snail family transcriptional repressor 2 (SLUG), signal transducer and activator of transcription 3 (STAT3), and SMAD family member 3 (SMAD3) in cancer cells." (PMID 41335176, 2025). "Similarly, RBM47-induced splicing changes were seen in genes such as SLK, MDM4 and TNC, all of which are genes with known functions in cancer." (PMID 24898756, 2014).
bacterial infections (1 paper, 2025). "These signaling pathways are intimately linked to immunity and inflammation, hinting at a possible function of RBM47 in regulating the body’s protective responses against bacterial infections." (PMID 39757245, 2025).
infection (1 paper, 2019). The state of being infected such as from the introduction of a foreign agent such as serum, vaccine, antigenic substance or organism. "To explore the influence of Rbm47 on IL-10 production in B cells, we attempted to knock down Rbm47 expression in B cells through Rbm47-specific shRNA-expressing lentiviral infection." (PMID 29844590, 2019).
RBM47 also shares sentences with these, for which no sentence is quoted: gastric cancer (3 papers); non-small cell lung carcinoma (3); prostate carcinoma (2); acute lung injury (1); adenocarcinoma (1); asthma (1); cardiovascular diseases (1); colonic polyps (1); epilepsy (1); glioblastoma (1); head and neck cancer (1); Hepatitis B (1); Hepatitis C (1); intestinal inflammation (1); intestinal polyp (1); Lewis lung carcinoma (1); malignant glioma (1); pancreatic cancer (1); pulmonary fibrosis (1); triple-negative breast carcinoma (1); tuberculosis (1); viral infection (1).